ID3 (inhibitor of DNA binding 3)
Diseases named in the same sentence as ID3 in open-access papers (continued):
Sharing a sentence is not in itself a finding about the gene and the disease.
atherosclerosis (15 papers, 2013 to 2025). A disease characterized by the build-up of fatty material and calcium deposition in the arterial wall resulting in partial or complete occlusion of the arterial lumen. "Population-based studies have discovered single-nucleotide polymorphism (SNP) rs11574 in the coding region of ID3 gene is linked with atherosclerosis in the Diabetes Heart Study." (PMID 39846697, 2024). "Murine studies have provided clear evidence that loss of Id3 promotes atherosclerosis in both Apoe−/−." (PMID 33271747, 2020). "ID3 (inhibitor of DNA binding-3) was shown to be an upstream regulator to protects against the formation of atherosclerosis and the SNP in the coding region of the ID3 gene were directly associated with coronary artery pathology." (PMID 28903366, 2017). "Increased susceptibility to atherosclerosis has been reported to be associated with an ID3 single nucleotide polymorphism (SNP)." (PMID 28785583, 2017). "Population-based studies have found SNP (single nucleotide polymorphisms) rs11574 in the coding region of the human ID3 gene associated with subclinical atherosclerosis in the Diabetes Heart Study." (PMID 28785583, 2017). "Previous studies using genome-wide linkage analysis in humans and an interspecific genetic cross in mice identified risk for early MI and atherosclerosis associated with loci in which ID3 resides." (PMID 24603695, 2014). "ID3 has been implicated in vascular lesion formation in response to injury and in native atherosclerosis." (PMID 25090023, 2014). "T cells have important roles in atherosclerosis, and Id3 has been implicated in T cell maturation, differentiation, and T cell driven autoimmune disease." (PMID 24603695, 2014). "Indeed, Id3-/-ApoE-/- mice develop significantly more atherosclerosis compared to Id3+/+ApoE-/- mice, demonstrating a direct relationship between loss of Id3 and increased atherosclerosis." (PMID 40607379, 2025). "A loss of ID3 accelerates atherosclerosis development in ApoE-depleted mice fed an atherogenic diet, but here we found that the expression of genes involved in the lipid metabolism and atherosclerosis are increased after HIV infection and oxLDL treatment itself." (PMID 38397063, 2024). "Notably, biochemical analysis of the Id3 protein encoded by the allelic variant associated with atherosclerosis revealed an attenuated ability of the protein to perform its functions as a dominant negative regulator of gene transcription." (PMID 33271747, 2020). "The finding that the ID3 gene is associated with coronary artery pathology can be supported by the fact that Id3 is an atheroprotective transcription regulator which functions to regulate B cell homing and B cell–mediated protection from early atherosclerosis." (PMID 31126344, 2019). "ApoE−/− mice with B cell-specific knockout of the gene encoding the helix-loop-helix factor Id3, known to have attenuated diet-induced atherosclerosis, have increased numbers of B-1b cells and increased IgM secreting cells in PVAT relative to littermate controls." (PMID 28970806, 2017). "Additionally, adoptive transfer of Apoe−/− B cells to B cell deficient μMT Apoe−/− mice attenuated atherosclerosis, an effect that was lost when the Apoe−/− B cells were null for Id3." (PMID 24603695, 2014). "The finding that a SNP in a single gene could be associated with a complex polygenic disorder such as atherosclerosis is supported by the fact that Id3 regulates multiple genes within pathways and cell types linked to atherosclerosis." (PMID 24603695, 2014). "Identification of a SNP in the coding region of the human ID3 gene, associated with subclinical atherosclerosis in the Diabetes Heart study, raises the interesting possibility that ID3 may have a role in human atherosclerotic disease." (PMID 24603695, 2014).
atherosclerosis (continued). "This gene encodes a transcription factor that has been found to be protective against atherosclerosis; a common loss-of-function SNP in the human ID3 gene has been linked increased carotid intima-media thickness, an intermediate trait associated with a variety of cardiovascular outcomes." (PMID 24400021, 2013). "Investigations have established that Id proteins, notably Id3, are fundamental to cardiovascular health, impacting everything from heart formation to vascular disease, including atherosclerosis and pulmonary hypertension." (PMID 38674087, 2024). "ID3 expression is involved in the protective process of coronary artery disease and atherosclerosis." (PMID 37109540, 2023). "An additional role for CCR6 in the recruitment of B cells to the atherosclerosis-prone aorta that is controlled by inhibitor of differentiation-3 (Id3) has been recently revealed." (PMID 33572939, 2021). "Compared to control Apoe−/− mice, Id3−/−Apoe−/− mice had a dramatic reduction in aortic B cells and a marked increase in atherosclerosis." (PMID 24603695, 2014). "The majority of published data in murine models of atherosclerosis, link Id3 to B cell-mediated atheroprotection." (PMID 24603695, 2014). "For instance, ID3 has previously been studied in combination with lipoxygenase (12/15-LO), which is demonstrated to produce pro-inflammatory alterations in blood vessels that lead to the progression of atherosclerosis." (PMID 39846697, 2024). "ID3 has also been shown to play a complex role with atherosclerosis." (PMID 28785583, 2017). "Examining molecular mechanisms in mice has recognized ID3 as a unique transcription factor that may contribute to kidney disease and provide mechanistic links between atherosclerosis, hyperlipidemia, and kidney disease in humans." (PMID 28785583, 2017). "ID3 involvement in vascular disease has been studied together with the lipoxygenase (12/15-LO) which is known to generate proinflammatory changes in blood vessels that precede the development of atherosclerosis." (PMID 28785583, 2017). "Furthermore, ID3 reduces atherosclerosis formation, in addition to T cell differentiation and maturation, which has been demonstrated as playing an important role in atherosclerosis." (PMID 31126344, 2019). "ID3 is integral to vascular function, influencing both the movement and integrity of endothelial cells, and is a component of pivotal signaling pathways such as PI3K/AKT, atherosclerosis, NO, and VEGF signaling." (PMID 38674087, 2024).
glioma (14 papers, 2017 to 2025). A benign or malignant brain and spinal cord tumor that arises from glial cells (astrocytes, oligodendrocytes, ependymal cells). "ID1, ID2, and ID3 allele deletions in tumors in an in situ model of brain cancer decreased the amount of glioma stem cells, halted tumor growth, and increased the survival time of mice." (PMID 38195969, 2024). "In this study, Per2 and Id3 were expressed in glioma tissues and were shown to be associated with patient outcomes in glioma patients." (PMID 35599595, 2022). "Initially, we investigated the TCGA and CGGA databases and discovered that Per2 and Id3 are associated with the WHO glioma grade, 5-year survival rate, and prognostic risk, and the two genes appear to be negatively correlated with each other." (PMID 35599595, 2022). "When Per2 overexpression was induced in glioma cells with Id3 overexpression, Per2 alleviated the increased malignancy of glioma caused by Id3, as shown by multiple experiments." (PMID 35599595, 2022). "We analyzed TCGA and CGGA databases for seeking association among Per2, Id3, and clinical features in glioma." (PMID 35599595, 2022). "We discovered that Id3 OE caused glioma cells to proliferate faster than controls in CCK-8 assays and colony formation, while proliferation was inhibited when the transfected Per2 OE vector was present." (PMID 35599595, 2022). "Next, CCK8, colony formation, Transwell, wound healing assay, flow cytometry and xenografts in mice were used to acknowledge the effect of Per2 and Id3 in glioma." (PMID 35599595, 2022). "In this study, we analyzed the clinical significance and relevance of Per2 and Id3 in patients with glioma using bioinformatics combined with immunohistochemistry of clinical samples." (PMID 35599595, 2022). "ID3 expression is increased in advanced glioma, and high ID3 expression had a shorter overall survival time in glioma patients." (PMID 39281062, 2022). "But the role of Id3 research is insufficient and needs further to clarify its effects on proliferation and invasion in glioma." (PMID 35599595, 2022). "CCK-8 assay, colony formation assay, Transwell assay, the wound healing assay, flow cytometric, and Xenograft nude mice were used to acknowledge the impact of Per2 and Id3 on biological behavior of glioma." (PMID 35599595, 2022). "In this study, we employed multiple laboratory techniques to acknowledge the biological activities and processes of Per2 and Id3 in glioma." (PMID 35599595, 2022). "Based on these findings, we conjecture that Per2 regulates glioma through downstream Id3, and in this study, protein levels of Id3 were reduced when Per2 was overexpressed, while Id3 overexpression did not change the levels of Per2 protein." (PMID 35599595, 2022). "We investigated the downstream processes of Per2 and discovered that Per2, a tumor suppressor gene, inhibited glioma cell proliferation by downregulating Id3 expression in glioma." (PMID 35599595, 2022). "The databases were next used to examine the correlations between mRNA levels of Per2 and Id3, which revealed that they were inversely correlated in human glioma." (PMID 35599595, 2022). "The results showed that the Per2 mRNA expression was negatively correlated with the WHO grade, while the Id3 mRNA expression was positively correlated with the WHO grade in patients with glioma in TCGA and CGGA databases." (PMID 35599595, 2022). "By using a wide range of functional examples, overexpression of Per2 restrains malignant biological behaviors in glioma cells by many ways, while Id3 promotes malignant biological behaviors in glioma cells." (PMID 35599595, 2022). "In a study using human glioma cell line Hs683, candoxin, which is a three-finger neurotoxin purified from the venom of the Malayan krait (Bungarus candidus) snake has been shown to downregulate ID3 which inhibits glioma cell proliferation." (PMID 32891179, 2020).
glioma (continued). "The Id proteins also occur in cancer stem cells, for example in glioma stem-like cells (GSCs), where Id3 induction through the EGFR/Akt/Smad5 pathway leads to acquirement of GSCs characteristics and angiogenesis." (PMID 28122577, 2017). "There are few studies on the biological function of Id3, particularly in glioma." (PMID 35599595, 2022). "Based on these findings, we hypothesized that Per2 is involved in Id3 expression in gliomas, which we explored in subsequent experiments." (PMID 35599595, 2022). "Here, we aim to explore whether overexpression of Per2, a tumor suppressor gene, may inhibit the malignant phenotype of glioma based on regulating PTEN/AKT/Smad5/Id3 signaling pathway and would help to identify a novel target for clinical precision medicine." (PMID 35599595, 2022). "Taken together, these data show that Per2 mitigates glioma development by downregulating Id3." (PMID 35599595, 2022). "Meanwhile, Id3 was identified as downstream of the AKT pathway in glioma." (PMID 35599595, 2022). "As in this study, Id3 owns the same biological function in glioma." (PMID 35599595, 2022). "The protein levels of Per2 and Id3 in 59 glioma specimens were assessed using IHC." (PMID 35599595, 2022). "As reported in the literature, ID3 could promote the formation of stem-like cells and tumor angiogenesis in glioma and might serve as a therapeutic target of low grade gliomas." (PMID 32857727, 2020). "Inhibitor of differentiation 3 (ID3)-induced increases in IL-6 and IL-8 are significantly decreased by treatment with an EGFR inhibitor that directly dephosphorylates AKT in glioma cells." (PMID 36341365, 2022). "In glioma-initiating cell, pivotal for cancer initiation and recurrence, the treatment of a TGF-β type 1 receptor inhibitor led to a reduction in the expression levels of ID1 and ID3." (PMID 38658527, 2024). "Per2 and Id3 maintained separate prognostic abilities and had a negative connection in human glioma." (PMID 35599595, 2022). "High-grade glioma cells with high Id1 expression (but no Id2 and Id3 expression) show self-renewal capacity, whereas cells with low Id1 levels possess poor self-renewal capacity but proliferative potential." (PMID 28122577, 2017). "Vandeputte DA discovered Id3 expression to be highly correlated with WHO glioma grade in prior work but did not investigate whether it could be an independent prognostic factor." (PMID 35599595, 2022).
lung carcinoma (14 papers, 2013 to 2025). "Downregulation of the type I BMP receptors with siRNA or small molecule inhibitors (DMH2, DMH1) in lung cancer cells caused growth inhibition and cell death, which is associated with a down-regulation of Id1 and Id3." (PMID 27048361, 2016). "Downregulation of type I BMP receptors with siRNA and selective small molecule antagonists decreases the phosphorylation of smad-1/5 causing a decrease in expression of Id, Id2, and Id3 in lung cancer cell lines." (PMID 24160469, 2013). "A tumor suppressor gene Id3 was found to be associated to the progression of certain malignancies, and in lung cancer studies, researchers discovered that miR-212-5p promotes NSCLC growth and xenograft tumor creation in vivo by decreasing Id3 level and activating the PI3K/Akt pathway." (PMID 38169723, 2023). "Because FOXA1 and PGC1α were found to regulate ID1, ID2, and ID3 in lung cancer cells, we investigated the mechanistic impact of ID1 on the loss of FOXA1-mediated EMT in lung cancer cells." (PMID 35897813, 2022). "Ectopic expression of FOXA1 increased ID1, ID2, and ID3 mRNA in A549, H358, and Calu-1 lung cancer cells." (PMID 35897813, 2022). "In human lung cancer cells, overexpression of ID3 inhibits cell proliferation, migration, invasion, and tumorigenesis, although the underlying mechanisms remain undetermined." (PMID 34620174, 2021). "Inhibition of BMP receptors with small molecule inhibitors decreases growth and induces death of lung cancer cells, which involves the downregulation of Id1 and Id3 by a Smad dependent mechanism." (PMID 27048361, 2016). "We show that the basal BMP activity in lung cancer cell lines is an essential regulator of Id1, Id2, and Id3 expression." (PMID 23593444, 2013). "PGC1α was found to promote both ID1, ID2, and ID3 expression in lung cancer cells, suggesting that PGC1α-mediated expression of ID families might be dependent on the transcription factor that is activated by PGC1α." (PMID 35897813, 2022). "We found that PGC1α not only promotes ID1, but also ID2 and ID3 expression in lung cancer cells, suggesting that PGC1α-mediated expression of ID families might be dependent on the cellular context and transcription factors, which are activated by PGC1α." (PMID 33917757, 2021). "These genes have diverse cellular roles, among which RRBP1 functions in endoplasmic reticulum stress response and has been found upregulated in lung cancer, and overexpression of the ID3 transcriptional repressor has been reported to reduce lung cancer growth in vivo." (PMID 26556242, 2015). "Knockdown of Id3 significantly decreased cell growth and induced cell death of lung cancer cells." (PMID 23593444, 2013). "To find out if ID3 mediates protein-protein interactions, we applied a Y2H screening on two different cDNA libraries, one from human placenta (important for its broad spectrum of expressed genes) and another from human lung cancer (useful to observe potential disease-related interactions)." (PMID 28680062, 2017). "Next, we examined whether Id1 and/or Id3 regulates cell survival and growth of lung cancer cells." (PMID 23593444, 2013). "While our data imply a dominant role for ID1 over ID2 and ID3, purely based on the 5–10‐fold higher expression of ID1 in primary, liver, and lung cancer samples, a modest increase in ID2 and ID3 was also observed between the primary tumour and lung metastases." (PMID 40116596, 2025). "aimed at characterizing tumour-infiltrating lymphocytes from lung cancer patients, evaluated the co-expression of PD1 and ID3 in TILs." (PMID 39676870, 2024). "Our results showed a higher and more dominant expression of ID1 than those of ID2, ID3, and ID4, particularly in lung cancer cell lines." (PMID 33917757, 2021).
lung carcinoma (continued). "To examine the roles of IDRs in CBP, we performed yeast-two-hybrid screenings of placenta and lung cancer cDNA libraries, which demonstrated that the long IDR linking the KIX domain and bromodomain of CBP (termed ID3) can potentially bind to several proteins." (PMID 28680062, 2017). "Our studies suggested a greater role for Id3 in regulating BMP induced cell growth and survival of lung cancer cells than Id1." (PMID 23593444, 2013). "Moreover, high ID3 expression by silencing miR-212-5p expression suppressed the activity of the PI3K/Akt signaling pathway and consequently promoted apoptosis and inhibited proliferation in lung cancer cells." (PMID 36443709, 2022).